ZEB1 (zinc finger E-box binding homeobox 1)
Diseases named in the same sentence as ZEB1 in open-access papers (continued):
Sharing a sentence is not in itself a finding about the gene and the disease.
colorectal tumor (7 papers, 2011 to 2024). "ZEB1 has been associated with aggressive behavior of colorectal tumors and uterine cancers." (PMID 24403226, 2013). "These RNA-seq data suggested that contribution of ZEB1 to colorectal tumor growth occurred by coordinating cell metabolism under hypoxic conditions." (PMID 39193340, 2024). "Our study demonstrates a novel example of an activator role of ZEB1 for the epigenetic landscape in colorectal tumor cells." (PMID 32094334, 2020). "Furthermore, induction of pri-miR-200a resulted in downregulation of ZEB1, ZEB2, Snail and Slug in colorectal tumor xenografts." (PMID 21929751, 2011). "It must be considered that different CAF subpopulations alter the tumor itself and, as a matter of fact, co-cultures of mouse colorectal tumor organoids with iCAF, but not with myCAF, revealed a pronounced induction of markers of invasiveness (Zinc finger E-box-binding homeobox 1 (Zeb1) and Vim))." (PMID 35892828, 2022).
fibrosis (7 papers, 2014 to 2026). the formation of excess fibrous connective tissue in an organ or tissue in a reparative or reactive process. "ZEB1, traditionally associated with cancer metastasis, has recently been linked to cardiac fibrosis." (PMID 41563538, 2026). "In these paths, the IPF node is directly connected to either EMT pathway nodes (SNAI2, TWIST1 and ZEB1) or dinoprostone (a pulmonary fibrosis regulator that expresses β-catenin), which is linked to CTNNB1." (PMID 38349059, 2024). "The expression of mTOR and ZEB1 significantly correlated with the fibrosis score and pulmonary function change." (PMID 25358403, 2014). "Therefore, cathepsin S, PAR2, and ZEB1 regulate intestinal fibrosis development in mice." (PMID 35840034, 2022).
gastric adenocarcinoma (7 papers, 2012 to 2026). "The strong association between VIP and ZEB1 in stomach adenocarcinoma warranted further investigation." (PMID 37444395, 2023). "Notably, the strongest association observed was between VIP and ZEB1 in stomach adenocarcinoma (R = 0.76)." (PMID 37444395, 2023). "We identified for the first time in gastric adenocarcinoma SGC7901 cells that over-expression of miR-200a reduced levels of ZEB1, ZEB2 and N-cadherin and increase E-cadherin levels." (PMID 22211245, 2012). "In addition, Cong N and his colleague found that down-regulated microRNA-200 family was able to promote EMT through wnt/β-catenin pathway by targeting E-cadherin repressors ZEB1/ZEB2 in gastric adenocarcinoma." (PMID 24626466, 2014). "Herein, using the Cancer Genome Atlas (TCGA) stomach adenocarcinoma (STAD) dataset (Ualcan.path.uab.edu/analysis), we first analyzed the prognostic value of ZEB1 expression in STAD patients." (PMID 40092690, 2025).
prostate tumors (7 papers, 2013 to 2025). "Module 3 includes NTRK2, DDR2, and STAT5B, which have been associated with prostate tumor metastasis, and JAZF1, ZEB1, and BCL2, which have been linked to cancer progression and resistance to chemotherapy." (PMID 39347576, 2024). "The clinical relevance of ZEB1 was also determined through immunohistochemical tissue microarray assessment, revealing significantly increased ZEB1 expression in prostate tumours following docetaxel treatment." (PMID 28133913, 2017). "Interestingly, RBM6 inhibited prostate tumour migration when ZEB1 was highly expressed, and increased RBM6 inhibited tumour migration in enzalutamide‐resistant LNCaP cell lines." (PMID 39900560, 2025). "Thus, under normal conditions, RBM6 promotes prostate tumour cell migration, but in the context of high ZEB1 expression, it inhibits migration." (PMID 39900560, 2025). "While this effect was concluded to result from the alleviation of AR-mediated repression of Zeb1 expression, androgen depletion-induced EMT could also be driven by HIF-1α, as androgen deprivation caused hypoxia in prostate tumors." (PMID 25821081, 2015). "Moreover, Zeb1+ epithelial cells can be detected in mouse and human prostate tumors." (PMID 32024836, 2020). "This study found that RBM6 can promote the migration ability of prostate tumours through CDH1, and its expression is regulated by ZEB1 transcription." (PMID 39900560, 2025). "Our findings reveal that RBM6 promotes the migratory capacity of prostate tumours by inhibiting CDH1, and its activity is also regulated by the key transcription factor ZEB1 of the EMT pathway." (PMID 39900560, 2025).
renal carcinoma (7 papers, 2015 to 2022). A carcinoma arising from the epithelium of the renal parenchyma or the renal pelvis. "Recent studies have indicated that NUCB2/NESF-1 enhanced migration, invasion, and EMT properties of colon and renal cancer cells through AMK/TOC1/ZEB1 pathway activation." (PMID 34361082, 2021). "Other studies, however, showed that miR-200c-3p decreases the metastatic ability of renal carcinoma cells by upregulating E-cadherin through ZEB1." (PMID 26002553, 2015). "We also found a positive correlation between PVT1 and BMI1, ZEB1 and ZEB2 as well as a negative correlation between miR-200c and PVT1, BMI1, ZEB1 and ZEB2 in our 50 paired renal cancer tissues through RT-PCR, which was consistent with that of the analysis from TCGA Data Portal." (PMID 29156724, 2017).
type 2 diabetes (7 papers, 2018 to 2025). "In conclusion, Zeb1 deficiency mainly affects the endocrine compartment, leading to altered glucose and insulin levels that result in systemic effects by exacerbating disease pathology of type 2 diabetes including accelerated liver steatosis." (PMID 34112759, 2021). "MiR-200 demonstrates a pro-inflammatory response by its effect on the synthesis of the protein Zeb-1, which is involved in increasing the activity of the cyclooxygenase-2 and monocytic chemotactic protein-1 in vascular smooth muscle cells in type 2 diabetes." (PMID 40217882, 2025). "In type 2 diabetic mouse models, miR-200b and miR-429 mimics can target and downregulate ZEB1, upregulate COX-2 and MCP-1, increase the expression of inflammatory factors in myocardial tissue, promote myocardial cell apoptosis, and cause myocardial damage, leading to cardiac disease." (PMID 40997050, 2025). "Additionally, miR-200 (in particular miR-200c) has been shown overexpressed in pancreatic islets in diabetic mice and lead to ß-cell apoptosis through a Zeb1 independent pathway and possibly through Ypel2, a potential oncogene, leading to type 2 diabetes." (PMID 38978141, 2024).
brain tumors (6 papers, 2013 to 2025). "Furthermore, the dysregulation of miR-200c-ZEB1 axis has been implicated in various neurological disorders, including brain tumors and neurodegenerative diseases." (PMID 39129166, 2025). "ZEB1 as a key element of EMT promotion has been extensively studied in different brain tumors, particularly GBM." (PMID 36402997, 2022). "Mesenchymal stem-like cells expressed C5a contribute to ZEB1 expression and brain tumor invasiveness through the stimulation of p38 mitogen-activated protein kinase." (PMID 36402997, 2022). "A comprehensive histological analysis of ZEB1 in different brain tumors showed that ZEB1 activation correlates with increasing tumor malignancy grade." (PMID 28556516, 2017). "In summary, we found that invasive cells can be distinguished from a xenografted brain tumour mass by their expression of ZEB1." (PMID 23818228, 2013). "Our data identify ZEB1 as a regulator of malignant glioma invasion, which is further corroborated by immunohistochemistry in specimens of invasive brain tumours of different grades." (PMID 23818228, 2013). "Further investigation is now needed to find out whether the activity of the Sonic Hedgehog gene regulates Zeb1 activity, and to discover whether inhibiting Zeb1 could prevent brain tumours from developing." (PMID 27178982, 2016). "ZEB1 and EMT have intensively been studied in carcinomas and has sparked several investigations of ZEB1 in primary brain tumors where it has been proposed to mediate response to hypoxia and increase proliferation, cell migration and invasion." (PMID 28945795, 2017).
Hyperglycemia (6 papers, 2021 to 2025). An increased concentration of glucose in the blood. "It was found that hyperglycemia diminished the physical association of ZEB1 with E-cadherin, resulting in a loss of control over E-cadherin repression which is known to cause the microvascular endothelial dysfunction commonly observed in DM." (PMID 34746916, 2021). "Long-term exposure to hyperglycemia and M1 macrophages led to the most pronounced increase in Zeb1 mRNA levels in benign PDEC, leading to a significant 3.79-fold elevation compared with the equivalent normoglycemic monoculture." (PMID 34064969, 2021). "In summary, these data support the view that concomitant exposure to M1 macrophages and hyperglycemia amplifies alterations in the mRNA levels of EMT and CSC transcription factors, most dominantly of Zeb1, in PDEC." (PMID 34064969, 2021). "Additionally, they found that MALAT1 was involved in hyperglycemia-induced EMT in human HaCaT cells by interacting with miR-205 and promoting the levels of Zinc Finger E-box Binding Homeobox 1 (ZEB1)." (PMID 39439564, 2024). "It has a powerful effect on TGF-β production through several mechanisms: negative regulation of TGF-β E-box repressor –Zeb1/2 and targeting of Smad-interacting protein 1 (SIP1), which is another E-box repressor; another mechanism is represented by hyperglycemia (diagnosed in half of our patients)." (PMID 38549763, 2024). "While hyperglycemia did not impact Zeb1 mRNA levels in H6c7-kras cells at any time of analysis, it led to a clear induction in H6c7-pBp cells." (PMID 34064969, 2021).
lung squamous cell carcinoma (6 papers, 2018 to 2025). "More importantly, the overexpression of ZEB1 has been found in lung squamous cell cancer, whose aberrant expression is involved in the occurrence, development and invasion of lung squamous cell cancer." (PMID 34257531, 2021). "In addition, SNHG1 plays an oncogenic role in lung squamous cell carcinoma through ZEB1 signaling pathway by inhibiting TAp63." (PMID 29872497, 2018).
malignant glioma (6 papers, 2013 to 2021). A grade III or grade IV glioma arising from the central nervous system. "Apart from upregulating ZEB1, ZEB1-AS1 is suggested to sponge miR-1224-5p, which has been identified as a tumor suppressor in malignant gliomas." (PMID 34638331, 2021). "The current research has shown EMT-like changes in malignant gliomas, including a role for SNAIL1/SNAIL2, TWIST1/ TWIST2, ZEB1/ZEB2 and miRNAs as inducers for a cell-invasive phenotype in GBMs." (PMID 26761212, 2016). "EMT-like changes in malignant gliomas are attributed to TWIST1, ZEB1/ZEB2 and SNAIl1/SNAIl2 as inducers for cell-invasiveness in GBMs." (PMID 24475040, 2014). "Our findings indicate that this regulator of epithelial-mesenchymal transition orchestrates key features of cancer stem cells in malignant glioma and identify ROBO1, OLIG2, CD133 and MGMT as novel targets of the ZEB1 pathway." (PMID 23818228, 2013). "We found that the expression levels of MMP‐2, MMP‐9, ZEB1, N-cadherin, and Integrin β1 significantly diminished in the siRNA1-RACK1 and siRNA2-RACK1 groups, suggesting that siRNA-RACK1 might suppress migration and invasion of malignant glioma cells by inhibiting the EMT signaling pathway." (PMID 27763568, 2016).
uveal melanoma (6 papers, 2017 to 2025). A melanoma derived from melanocytes of the uveal tract. "Through ligation of 4-1BB, NK cells induced the expression of the ZEB1 transcription factor, leading to the formation of liver metastasis of uveal melanoma." (PMID 38191418, 2024). "We intended to clarify this heterogeneity in uveal melanoma (UM) by looking for evidence of cancer stem cell involvement and a potential role of ZEB1 in cancer cell plasticity." (PMID 35404029, 2022). "Furthermore, Zeb1 has also been identified as a critical oncogenic regulator in uveal melanoma." (PMID 33291663, 2020).
viral infection (6 papers, 2017 to 2025). "Consistently, both THP-1 and KALS1 cell lines showed higher expression levels of MIAT and ZEB1 after stimulation of poly (I:C), a synthetic analog of double strand RNA representing active viral infection, a potential trigger of ME/CFS." (PMID 30119681, 2018). "In an attempt to delineate the molecular mechanism underlying leukemogenesis after viral infection, genetic and expression analyses revealed that the TCF8 gene (ZEB1) was frequently altered by epigenetic dysregulation." (PMID 32309604, 2018). "P. gingivalis colonization inhibited IFNλ production after viral infection by suppressing IRF1 and STAT1 activation and transcriptionally repressing IFNλ1 production via zinc finger E-box binding homeobox 1 (ZEB1)." (PMID 37278532, 2023).
adult T-cell leukemia (5 papers, 2018 to 2023). "ZEB1 is also downregulated in other malignant T-cell diseases, specifically Adult T-cell Leukemia/Lymphoma (ATLL), driven by infection with HTLV-1, and cutaneous T cell lymphoma (CTCL)." (PMID 37600794, 2023). "In the context of adult T-cell leukemia (ATL), ZEB1 functions as a tumor suppressor but is frequently disrupted through various mechanisms." (PMID 38002949, 2023). "On the contrary, ZEB1 is a candidate tumor suppressor gene in adult T-cell leukemia/lymphoma (ATLL), where it contributes to TGF-β1-mediated growth suppression resistance of malignant CD4+ T cells and ZEB1 mutant mice frequently undergo spontaneous CD4+ T-cell lymphomas." (PMID 30518749, 2018).
atherosclerosis (5 papers, 2013 to 2025). A disease characterized by the build-up of fatty material and calcium deposition in the arterial wall resulting in partial or complete occlusion of the arterial lumen. "We found that exogenously induced expression of ZEB1 in Zeb1∆M macrophages reduced intracellular lipid accumulation, increased cholesterol efflux and reduced the atherosclerosis plaque." (PMID 38097578, 2023). "The study uses human endarterectomies and a mouse model where Zeb1 expression is specifically knocked out in myeloid cells and that is later crossed with the atherosclerosis-prone ApoeKO mouse." (PMID 38097578, 2023). "To investigate a potential role for ZEB1 in atherosclerosis, we first examined plaque formation in a constitutive Zeb1-deficient mouse." (PMID 38097578, 2023). "At the end of the 10 weeks protocol on the Western diet, Zeb1∆M/ApoeKO mice exhibited heavier livers with increased lipid deposits compared to Zeb1WT/ApoeKO mice, suggesting that Zeb1 ablation in macrophages has other systemic effects beyond aggravating atherosclerosis." (PMID 38097578, 2023). "Collectively, the findings presented here establish ZEB1 as an anti-atherogenic factor in macrophages, suggesting that increasing its expression could be a potential therapeutic strategy for atherosclerosis in patients with low ZEB1 levels." (PMID 38097578, 2023). "Here we focused on five genes (Tgfbr1, Zeb1, Hdac2, Rab5a, and Ets1), which were all identified by miFDR alone, and discussed their potential roles in the context of diesel particle exposure and atherosclerosis." (PMID 24564975, 2013). "The expression level of Vimentin, N-cadherin, Snail1, ZEB1, PI3K, p-AKT, p-mTOR and BAX in atherosclerosis and chronic stress were higher than that in control group." (PMID 37642954, 2023). "• Zeb1 (up-regulated in DE-rats by 1.43 folds) mediates TGF-beta signaling in vascular disease and vascular smooth muscle cell differentiation during development (L3), which eventually leads to atherosclerosis." (PMID 24564975, 2013). "For instance, the lncRNA PSMB8-AS1 is markedly elevated in human atherosclerotic plaques and promotes vascular inflammation and atherosclerosis by regulating the NONO/PSMB9/ZEB1 axis, demonstrating that it is possible to develop lncRNA-based strategies to combat cardiovascular disease." (PMID 41219994, 2025).
COVID-19 (5 papers, 2020 to 2023). A disease caused by infection with severe acute respiratory syndrome coronavirus 2. "For instance, we observed significantly stronger enrichment of TBX21 (adjusted P = 1 × 10−224), RUNX3 (adjusted P = 1 × 10−199), TCF7L2 (adjusted P = 1 × 10−167) and ZEB1 (adjusted P = 1 × 10−118) motifs in severe COVID-19 risk variant-depleted cells." (PMID 35668323, 2022). "MiRNAs that were downregulated in serum of COVID-19 patients mainly target genes promoting angiogenesis (e.g., VEGFA, ANGPT2, COL4A1, FGF2, ZEB1), apoptosis, autophagy, stress response (e.g., ATG12, ATG14, ATG2B, SOD2, TXNIP), and inflammation (e.g., CXCL9, CXCL10, IL1R1, TNF)." (PMID 36032130, 2022).
Infertility (5 papers, 2022 to 2026). "Loss of miR-200a/b regulation of Zeb1 caused anovulatory infertility and reduced LH expression in female mice." (PMID 41533591, 2026). "Using gene-edited mice that express a miR-200a/b-resistant form of Zeb1, we found that derepression of Zeb1 in the female pituitary caused decreased production of luteinizing hormone and anovulatory infertility." (PMID 41533591, 2026). "PG-enriched motifs also include ZEB1, which has been linked to anovulation and infertility in mice lacking the microRNAs that target ZEB1 in the pituitary gland." (PMID 40483385, 2025). "In contrast, ZEB1 mRNA expression was relatively high in infertile tissues." (PMID 37894829, 2023).
invasive carcinoma (5 papers, 2011 to 2025). A carcinoma that is not confined to the epithelium, and has spread to the surrounding stroma. "The expressions of N-cadherin, Snail, Twist, Vimentin and Zeb1, and number of cells that demonstrated loss of E-cadherin were significantly higher in invasive carcinomas in contrast to normal tissue and DCIS samples (p < 0.05)." (PMID 31889895, 2019). "In line with all these studies, our results also demonstrated that there was a significantly higher rate of E-cadherin loss and higher expressions of N-cadherin, Snail, Twist, Vimentin and Zeb1 in invasive carcinoma in comparison to DCIS." (PMID 31889895, 2019). "The current investigation explores the expression of EMT markers (N-cadherin, Snail, Twist, Vimentin, Zeb1, E-cadherin) in invasive carcinomas and DCIS." (PMID 31889895, 2019). "N-cadherin, Snail, Twist, Vimentin, and Zeb1 were expressed in 19.8% (23/116), 19% (22/116), 9.5% (11/116), 16.4% (19/116),and 12.9% (15/116) of the invasive carcinomas." (PMID 31889895, 2019). "As a repressor of E-cadherin, ZEB-1 is highly expressed in invasive carcinomas, at the invasive front of tumors in dedifferentiated cancer cells." (PMID 31776338, 2019). "Stromal zeb1 expression was significantly lower in ductal in situ carcinomas than in invasive carcinomas (p = 0.020)." (PMID 21324165, 2011). "Studying the gene expression or the amount of N-cadherin protein, which is upregulated in invasive carcinomas, of the transcription factors Snail, Slug, Twist, and Zeb1/2, and of matrix-degrading enzymes, would help to understand and establish whether there is indeed a specific effect." (PMID 40724592, 2025).